BRAF (B-Raf proto-oncogene, serine/threonine kinase)
Diseases named in the same sentence as BRAF in open-access papers (continued):
Sharing a sentence is not in itself a finding about the gene and the disease.
melanoma (continued). "Resistance to BRAF inhibitors in BRAF-mutant melanoma cells can occur through diverse molecular mechanisms that converge on reactivation of the BRAF-MEK-ERK signaling pathway." (PMID 35580987, 2022). "CheckMate 066 was a phase III trial, which compared nivolumab monotherapy vs. dacarbazine as the first-line treatment for BRAF wild-type naive for the treatment of advanced melanoma." (PMID 36844955, 2022). "One study investigated the value of BRAF V600E MAF variability within primary melanomas (MMp) and its potential prognostic implications." (PMID 35814395, 2022). "As our data show that DUSP4 depletion leads to cell death through MITF suppression, we evaluated the sensitivity of BRAF/NRAS–mutant melanoma cells expressing either high or low levels of MITF to DUSP4 knockdown." (PMID 35580987, 2022). "Acquired resistance of melanoma patients to BRAF (brafi) and MEK (MEKI) inhibitors that block the mitogen-activated protein kinase (MAPK) pathway limits their long-term use." (PMID 36124033, 2022). "Acetoacetic acid (AcAc), the metabolic precursor of BHB was recently reported to confer tumor-accelerating effects of a KD in BRAF mutant melanoma-bearing mice." (PMID 35851093, 2022). "An internal splice variant of BRAF V600E, which lacks exons 2-8, a region encoding RBD, is recurrently observed in treatment refractory melanoma patients to RAF inhibitor (RAFi) at a frequency of 13-30% 76-80." (PMID 35966590, 2022). "Oncogenic mutations in genes are widely observed in melanoma, with MEK, BRAF, NRAS, and NF1 being the most common ones." (PMID 35719931, 2022). "Vemurafenib (PLX4032) is a novel small molecule BRAF inhibitor that has been approved by the US Food and Drug Administration for the treatment of patients with melanoma." (PMID 36524001, 2022). "Based on BRAF, NRAS and TERT promoter mutations, the custom melanoma panel displayed a limit of detection of ~0.2% mutant allele frequency and showed significant correlation with droplet digital PCR." (PMID 35494035, 2022). "The development of inhibitors targeting MEK1/2 kinases, has yielded the non-ATP-competitive allosteric inhibitors trametinib, cobimetinib and binimetinib, which brought hope for non-BRAF-mutant melanoma cases." (PMID 36358912, 2022). "The median time to the initiation of BRAF plus MEK inhibitors since the diagnosis of melanoma and diagnosis of brain metastases were 36.9 months and 3.9 months, respectively." (PMID 36579260, 2022). "BRAF-mutant human melanoma cell lines increased the expression of vascular endothelial growth factor (VEGF), which promoted a tolerogenic DC phenotype and tumor progression by sustaining neoplastic angiogenesis." (PMID 36016960, 2022). "Patient 1 is a 60-year-old Caucasian female with BRAF wild type unknown primary (tumor mutation burden 4 mutations/megabase) metastatic melanoma to bone, lung, and soft tissue who originally presented with a renal mass and had a nephrectomy positive for melanoma." (PMID 36045435, 2022). "Mutant BRAF activates the pathway downstream of Ras abnormally in melanomas, bypassing this feedback loop." (PMID 35999349, 2022). "In a phase III randomized clinical trial (METRIC), the efficacy of trametinib vs. dacarbazine was tested in patients with advanced stage or metastatic BRAF V600 E/K mutant-positive melanoma." (PMID 36699049, 2022). "In 2015, both the FDA and European Medicines Agency approved cobometinib, a potent, selective oral MEK1/2 inhibitor that can be taken with the B‐rapidly accelerated fibrosarcoma (BRAF) inhibitor vemurafenib for the treatment of malignant melanoma." (PMID 36349142, 2022). "Eighty-one patients (88, 73.9%) had BRAF wild-type melanoma, whereas only 31 (26.1%) patients harbored the BRAF V600 mutation." (PMID 35885042, 2022). "Certain CCAs have BRAF-V600E mutations, as seen in other forms of malignancies such as CRC and melanoma." (PMID 35681621, 2022).
melanoma (continued). "Similar to the traditional histological subclassification of melanoma, today the molecular classification is also possible where there are four major categories, the BRAF-mutant, the RAS-mutant, the NF1-mutant and the so-called triple wild-type forms." (PMID 35628196, 2022). "Patients with metastatic BRAF V600 mutant melanoma, which accounts for 40–50% of melanoma patients, are treated with MEK inhibitors such as trametinib, cobimetinib, selumetinib, and binimetinib." (PMID 35954441, 2022). "DMF enhances the anti-melanoma efficacy of vemurafenib, a BRAF inhibitor, by suppressing multiple signaling pathways." (PMID 35955813, 2022). "The most frequently sampled conformers of NRAS61R and NRAS61K bound BRAF with the highest affinity, followed by the third most common mutant in human melanoma, NRAS61L." (PMID 35672316, 2022). "For example, BRAF inhibitors were used in melanoma therapy, and MS-based chemical proteomics were used to identify never-in-mitosis-gene-A related kinase 9 (NEK9) and CDK16 as unique targets of dabrafenib." (PMID 36338621, 2022). "We used two-color PALM to study the dynamics of NRas and BRAF organization at the PM of live (108T) melanoma cells, in single molecule detail." (PMID 36304112, 2022). "We first verified the association of SEMA6A protein expression with BRAF mutation in the RECI1 cohort, which includes 112 metastatic advanced melanoma patients surgically treated at the Regina Elena National Cancer Institute." (PMID 35440004, 2022). "In another study, a double-blind phase III randomized control trial, a comparison was made between dabrafenib monotherapy and trametinib and dabrafenib combination therapy in patients with BRAF mutant melanoma (COMBI-d)." (PMID 36699049, 2022). "Because 108T cells contain only wt BRAF, we studied the effects of vemutrafenib in A375 melanoma cells that express BRAFV600E." (PMID 36304112, 2022). "FoundationOne CDx, initially approved in 2017, is the third device approved for detection of V600E in melanoma, with prior devices approved in 2013 and 2016 (THXID BRAF Assay Kit and Cobas 4800 BRAF V600 Mutation text, respectively)." (PMID 35689144, 2022). "To directly determine the pro-tumorigenic effect of NAMPT we over-expressed the enzyme in the melanoma Mewo cell line (BRAF-WT) and in NIH-3T3 (murine immortalized fibroblasts), very commonly exploited in this kind of experiments." (PMID 35272691, 2022). "BRAF inhibition (BRAFi) also renders BRAFV600 melanoma cells addicted to oxidative phosphorylation (OXPHOS) by releasing BRAF mediated inhibition of a MITF-PGC1α-OXPHOS pathway." (PMID 35232962, 2022). "AC-93253, a SIRT 2 inhibitor, and AR42, a phenyl-butyrate-based HDACi, are pivotal in reinstalling melanoma cell sensitivity to BRAF inhibition." (PMID 35409020, 2022). "This work also shows that BRAFi and MEKi, as solo or combined treatments in vitro, decreased soluble MICA, MICB and ULBP2 in supernatants from BRAF-mutant melanoma cells." (PMID 36726591, 2022). "It is clear that BRAF oncogenic signaling has emerged as a critical regulator of this metabolic pathway in melanoma." (PMID 36077374, 2022). "This combination was also effective in inducing cell death in melanoma cells resistant to BRAF and MEK1/2 inhibitors." (PMID 36581992, 2022). "NGS testing detected key driver alterations at expected prevalence rates: lung EGFR (16%), ALK (3%), RET (1%), melanoma BRAF (43%), colorectal RAS/RAF (67%), among others." (PMID 35323313, 2022). "Another study showed that the p300 inhibitor C646 can overcome the resistance of melanoma cells to BRAF inhibitors in vitro and in vivo, which also provides a theoretical basis for targeted combination therapy." (PMID 36125617, 2022). "It has to be emphasized that the KIT receptor signaling pathway, containing NRAS and BRAF, is the dominating pathway in melanocytes (and evidently in melanoma), and it is responsible for activating the melanocyte-specific transcription factor MITF." (PMID 35628196, 2022).
melanoma (continued). "Currently, according to the genotype and stage of melanoma, targeted therapy, such as BRAF inhibitors and MEK inhibitors, has been used as first-line treatment or adjuvant therapy for patients." (PMID 35906389, 2022). "BRAF-activated melanomas are characterized by a suppressed level of microphthalmia-associated transcription factor (MITF) and thus a low PGC-1α expression, which leads to attenuated mitochondrial function." (PMID 36003368, 2022). "In melanoma treated with BRAF inhibitors, it has been demonstrated that autophagy is induced and is responsible for drug resistance." (PMID 35681591, 2022). "In the phase III CheckMate 066 trial, a 5-year overall survival (OS) rate of 39% was reported with nivolumab monotherapy in treatment-naive patients with wild-type BRAF advanced melanoma." (PMID 35565428, 2022). "For targeted therapy the gold standard consists in the combination therapy with BRAF and MEK inhibitors (MAPKi) directed at blocking the BRAF/MEK/MAPK signaling pathway in BRAFV600 mutated melanomas." (PMID 36438490, 2022). "The samples at different time points were collected from a BRAF-mutant melanoma patient who developed an early resistance to dabrafenib/trametinib." (PMID 36077693, 2022). "S100A9 is suggested to have a role in acquired resistance to BRAF inhibitors and in melanoma metastasis." (PMID 36139698, 2022). "Increased expression of PD-1 and its ligand, PD-L1, has been reported in advanced melanoma patients treated with BRAF inhibitors." (PMID 36125617, 2022). "Comprehensive characterization of these novel targets is a clear next step in understanding their clinical utility in frontline‐treatment selection for patients with BRAF‐mutant melanoma, as biomarkers of treatment resistance, and their diagnostic potential." (PMID 36911295, 2022). "Immunoblot analysis also suggested that upon BRAF inhibition, the levels of proliferative markers were higher in melanoma cells on MAF‐ and FRC‐derived ECMs than on HDF‐derived ECMs." (PMID 34957688, 2022). "Low STK17B was similarly correlated with worse DSS in T and M Stage, pathologic stage, melanoma Clark level, Breslow depth, melanoma ulceration, tumor site, BRAF status, age, race, gender, radiation therapy of SKCM patients." (PMID 35171924, 2022). "In melanoma, G9 synergizes with a BRAF inhibitor and an MEK inhibitor to enhance apoptosis signaling, increase sensitivity to targeted therapies, reverse resistance to vemurafenib in vitro, and reduce tumor growth in vivo." (PMID 35884430, 2022). "Another group studied the role of EVs in developing resistance to BRAF inhibition in melanoma cells." (PMID 36289847, 2022). "To assess the impact of DUSP4 depletion on the activation of various MAPKs in cells, we measured the phosphorylated form of ERK and the two stress-activated MAPKs JNK and p38, after DUSP4 down-regulation in BRAF-mutant melanoma cells." (PMID 35580987, 2022). "Inhibition of RSK2 can enhance sensitivity of BRAF mutant melanoma cells to vemurafenib and overcome vemurafenib resistance." (PMID 36210843, 2022). "Another critical autophagy regulator ATG5 is documented to be downregulated in the early stage of melanoma, enabling the bypass of BRAF-induced senescence and contributing to the proliferation of melanoma cells." (PMID 36003368, 2022). "Those with metastatic BRAF V600E mutant melanoma treated with targeted therapy in the COMBI-d study (NCT01584648) had prolonged PFS and OS if ctDNA was cleared at week 4 after treatment initiation." (PMID 35347327, 2022). "In the setting of MAPK inhibition with vemurafenib in patients with advanced BRAF mutant melanoma, greater than 80% inhibition of ERK phosphorylation correlated with clinical response." (PMID 37359242, 2022). "According to the recent ASCO guidelines, the first choice as adjuvant therapy for patients with resected stage IIIA/B/C BRAF wild-type melanoma consists of 52 weeks of nivolumab or pembrolizumab." (PMID 36844955, 2022).
melanoma (continued). "The potential mechanism involves the upregulation of PERK (EIF2AK3), inhibition of which restores the sensitivity of PTEN-impaired melanoma cells to BRAF inhibitor." (PMID 35565444, 2022). "Regarding the MAPK inhibitors, the therapy combining BRAF and MEK inhibitors has proven its effectiveness in the treatment of V600 BRAF-mutated melanoma." (PMID 35158770, 2022). "Although BRAF inhibition in melanoma cells is partially acting via down-regulation of GLUT-1 and GLUT-3, this is totally reversed upon resistance development as it was shown in in vitro melanoma models and in vitro patient samples." (PMID 35406796, 2022). "BRAF mutant tumors (melanoma, lung adenocarcinoma anaplastic thyroid- or colon cancer) can be treated by BRAF inhibitors." (PMID 36213163, 2022). "Melanomas bearing BRAF-V600E mutation tend to display peculiar clinical features and show a more aggressive behavior than BRAF wild-type melanomas." (PMID 36009541, 2022). "We next investigated the role of UHMK1 in the regulation of proliferative and metabolic responses to BRAFi in a panel of BRAF mutant melanoma cell lines." (PMID 35232962, 2022). "Targeted therapy for BRAF-mutant (BRAF-MT) mCRC was prosed based on the successful outcomes of BRAF inhibition in melanoma." (PMID 35625987, 2022). "There are some studies of miR-211-5p on the regulation of tumor drug resistance; miR-211-5p can enable resistance to BRAF inhibitors in melanoma." (PMID 35311096, 2022). "We have previously shown that overexpression of either SETDB1 or SUV39H1, two histone 3 lysine 9 (H3K9) methyltransferases, cooperate with oncogenic BRAF(V600E) to accelerate melanoma formation." (PMID 35223844, 2022). "Only 3 (6.4%) of the identified 47 CDx devices contained therapeutic class labeling, with two devices targeting EGFR mutations for the treatment of NSCLC and one targeting BRAF V600E and BRAF/MEK inhibitor combinations for melanoma." (PMID 35689144, 2022). "Patients with advanced stage IIIc and stage IV NM and SSM treated with anti-CTLA-4 and/or anti-PD-1, or BRAF/MEKi in the first line, were included from the prospective Dutch Melanoma Treatment Registry." (PMID 36428787, 2022). "BRAF and NRAS are the most frequently affected oncogenes in acral melanomas but at a lower frequency compared to sun-exposed melanomas, whereas KIT mutations are more common in acral melanomas." (PMID 35197475, 2022). "In vemurafenib-resistant BRAF-mutant melanoma, active SREBP-1, the downstream target of BRAF signaling, was the characteristic to sustain lipogenesis and up-regulate the expression of FASN." (PMID 35646898, 2022). "Studies based on double-mutant engineered melanoma cells containing NRAS and BRAF activating mutations showed that the expression of the two genetic alterations can induce cell senescence because of an overactivation of the RAS/RAF/ERK pathway." (PMID 35580987, 2022). "Increased expression of class I HDACs has been reported in cell lines derived from patients with BRAF inhibitor-resistant melanoma, indicating that HDACs are possibly involved in the development of acquired resistance to BRAF inhibitors." (PMID 35055045, 2022). "An expanded analysis that profiles the response of BRAFi-resistant melanoma cells to mitotic inhibitors is necessary to fully elucidate the molecular features predictive of response to the combination of BRAF inhibitors and mitotic inhibitors." (PMID 35444937, 2022). "To further explore the mechanism of lj‐2‐66 in melanoma, we performed RNA‐seq on BRAF‐mutant melanoma cells after lj‐2‐66 treatment and used the Kyoto Encyclopedia of Genes and Genomes (KEGG) database to analyse differentially expressed genes." (PMID 35332658, 2022). "The aim of this work was to evaluate metabolic imaging using 13C-MRS (Magnetic Resonance Spectroscopy) as a marker of response to BRAF/MEK inhibition in a syngeneic melanoma model." (PMID 35327519, 2022).
melanoma (continued). "The A375 amelanotic cell line carries mutations on BRAF and CDKN2 genes, usually linked to melanoma caused by sun damage." (PMID 35408947, 2022). "Similar results were obtained in the in vivo study on the CHL-1 mice line BRAF wild-type melanoma xenografts, where the addition of CBD to THC enhanced the inhibition of tumor growth." (PMID 35743195, 2022). "Treatment of patients with BRAF(V600E) melanoma with BRAF and MEK inhibitors such as dabrafenib and trametinib have proven to prolong patient survival." (PMID 35368039, 2022). "Among the BRAF WT primary melanomas, 33.3% (8/24) further progressed to distant metastatic tumors, and 87.5% (7/8) of them died of melanoma." (PMID 35326682, 2022). "BRAF inhibitor-resistant melanoma cells expressed more iNAMPT and eNAMPT than sensitive cells in both experimental models and clinical samples." (PMID 36160449, 2022). "It is one of the proteins secreted by melanoma cells sensitive to the BRAF inhibitor during treatment." (PMID 35565444, 2022). "This study demonstrates that BRAFi-resistance, in at least a subset of melanoma cells, confers vulnerability to pharmacological disruption of mitosis and suggests a targeted synthetic lethal approach for overcoming resistance to BRAF/MEK-directed therapies." (PMID 35444937, 2022). "We predicted the drug response of RAF inhibitor (dabrafenib) and MEK inhibitor (trametinib) in three pre-treatment and matched post-relapse BRAF-mutant RAF/MEK inhibitor-resistant melanoma patients." (PMID 36167836, 2022). "For example, the tumor type in DepMap most sensitive to knockout of the BRAF kinase is melanoma, the disease in which BRAF inhibitors were first approved and are most widely used." (PMID 35737447, 2022). "Data in advanced melanoma have shown inferior outcomes with intermittent dosing of BRAF and MEK combination therapy." (PMID 36212431, 2022). "Overall, these results indicate that MAPK pathway de-inhibition through DUSP4 inactivation can potently impair the growth of BRAF-mutant melanoma cells." (PMID 35580987, 2022). "Then, RNA‐seq was performed to explore the mechanism of lj‐2‐66’s effect on BRAF‐mutant melanoma cells." (PMID 35332658, 2022). "Only 7.5% of the BRAF V600E/K mutant melanoma patients were prescribed adjuvant dabrafenib/trametinib in this setting." (PMID 35336796, 2022). "In the majority of BRAF-positive melanoma patients, combination therapy with BRAFi and MEKi eventually leads to the development of acquired resistance." (PMID 34837846, 2022). "We further analyzed the gene expression profiles of melanoma tissue samples obtained from patients before and after treatment with a BRAF signaling inhibitor (Gene Expression Omnibus accession GSE75299)." (PMID 35148308, 2022). "The randomized, phase 3 COMBI-I trial evaluated the efficacy of spartalizumab, dabrafenib and trametinib compared to placebo, dabrafenib and trametinib as first line treatment of patients with unresectable BRAF mutant melanoma." (PMID 36505793, 2022). "The aim of the present study was to explore the involvement of lipid metabolism in melanoma resistance and assess the effects of its targeting in cellular models of melanoma with acquired resistance to the BRAF-inhibitor PLX4032/Vemurafenib." (PMID 35912092, 2022). "Since 2005, 3 BRAF inhibitors have been approved for use in patients with BRAF mutant melanoma—first, vemurafenib and, subsequently, dabrafenib and encorafenib." (PMID 35492830, 2022). "Under PLX 4032 treatment, drug-resistant melanoma cells exhibited increased nuclear accumulation of YAP/TAZ and transcriptional activity, which, in turn, conferred resistance to BRAF inhibitors in BRAF V600E mutant melanoma cells." (PMID 35884430, 2022). "Patients with BRAF mutant melanoma and receiving targeted therapy will often show a dramatic reduction in melanoma burden, followed by recurrent melanoma growth from residual disease (or persister cells)." (PMID 35394030, 2022).